CD79B (CD79b molecule)
Description:
Required in cooperation with CD79A for initiation of the signal transduction cascade activated by the B-cell antigen receptor complex (BCR) which leads to internalization of the complex, trafficking to late endosomes and antigen presentation. Enhances phosphorylation of CD79A, possibly by recruiting kinases which phosphorylate CD79A or by recruiting proteins which bind to CD79A and protect it from dephosphorylation.
Synonyms: B29; IGB; Ig-beta; Igbeta; AGM6
Tractability: Small molecule: it has a high-quality binding pocket. Antibody: its Gene Ontology location is reachable by antibodies, with high confidence; UniProt places it where antibodies can reach, with medium confidence; UniProt predicts a signal peptide or a membrane-spanning region; the Human Protein Atlas places it where antibodies can reach. PROTAC: ubiquitination databases record sites on it; its protein half-life has been measured. Other modalities: an approved drug acts on it.
Gene: Protein-coding gene on chromosome 17 (63,928,738 to 63,932,629, reverse strand). Ensembl gene ENSG00000007312.
Subcellular location: Cell membrane
Subcellular location (Human Protein Atlas): Plasma membrane; Cytosol; Nucleoplasm
Pathways (Reactome):
Immune System: Antigen activates B Cell Receptor (BCR) leading to generation of second messengers; CD22 mediated BCR regulation
Disease: Potential therapeutics for SARS
Gene Ontology:
Molecular function: identical protein binding; protein binding; transmembrane signaling receptor activity
Biological process: B cell differentiation; B cell receptor signaling pathway; immune response; signal transduction; cell surface receptor signaling pathway; immune system process
Cellular component: B cell receptor complex; extracellular exosome; IgM B cell receptor complex; plasma membrane; external side of plasma membrane; membrane
Genetic constraint (gnomAD): Loss-of-function variants: 7 observed, 31.23 expected, observed/expected ratio (o/e) 0.22, 90% interval 0.13 to 0.42. The upper end of that interval is the gene's LOEUF score, 0.42, which puts it in group 1 of 6, group 1 being the genes least tolerant of losing a copy. Missense variants: 218 observed, 310.94 expected, observed/expected ratio (o/e) 0.7, 90% interval 0.63 to 0.78. Synonymous variants: 118 observed, 124.57 expected, observed/expected ratio (o/e) 0.95, 90% interval 0.81 to 1.1.
Gene-disease validity (ClinGen):
ClinGen rates the evidence that CD79B causes each of these diseases.
agammaglobulinemia 6, autosomal recessive (autosomal recessive): Definitive.
Cancer hallmarks: escaping programmed cell death (promotes)
Homologues: Orthologues: chimpanzee CD79B (99% identical), macaque CD79B (86% identical), dog CD79B (77% identical), guinea pig CD79B (74% identical), pig CD79B (71% identical), rat Cd79b (69% identical), mouse Cd79b (68% identical), rabbit CD79B (65% identical), zebrafish cd79b (29% identical), tropical clawed frog cd79b (28% identical). Paralogues in human: CD79A (25% identical).
Diseases named in the same sentence as CD79B in open-access papers:
CD79B is named in the same sentence as 73 diseases in open-access papers, as found by Europe PMC text mining. Sharing a sentence is not in itself a finding about the gene and the disease. The quoted sentences say what the papers report.
lymphoma (55 papers, 2009 to 2025). A malignant (clonal) proliferation of B- lymphocytes or T- lymphocytes which involves the lymph nodes, bone marrow and/or extranodal sites. "In conclusion, the obtained gene expression profile of CD79B-mutated DLBCLs improves the characterization of this lymphoma subpopulation and contributes to a better understanding of the complex molecular heterogeneity of DLBCL." (PMID 41295250, 2025). "Previous studies have demonstrated that lymphoma cells can unlock this oncogenic strategy through CD79B/A mutations, which result in increased BCR surface levels through hindered BCR internalization and loss of negative regulation by phosphorylation by LYN." (PMID 38630892, 2024). "These patients have previously been published as part of a prior study (n = 34) investigating MYC, BCL2, and BCL6 rearrangements, pathogenic variants of MYD88 and CD79B, and double-expressor lymphoma." (PMID 38542066, 2024). "On the other hand, genetic studies provided insights into the contribution of CD79a and CD79b (and their mutations) towards tumorigenesis and lymphoma development." (PMID 38203179, 2023). "MYD88, CD79B, and other NF-κB-pathway-related mutations promote IL-10 expression by lymphoma cells, and IL-10 has also been found to express in CD68+ and CD163+ tumor-associated macrophages by double immunostaining analysis." (PMID 36644235, 2023). "The main example of uneven distribution of CD79A and CD79B mutations between lymphoma subtypes is DLBCL." (PMID 38203179, 2023). "As an example of this complexity, CD79A and CD79B mutations were included in a large network of 153 lymphoma-altered genes related to NF-κB signaling." (PMID 38203179, 2023). "In lymphoma, CD79B mutations augment BCR surface levels via reduction of BCR endocytosis, preventing BCR binding to clathrin-coated pits." (PMID 38203179, 2023). "Forty‐five (40%) lymphomas had a CD79B mutation, including three cases with the Y196 hotspot mutation, and 26 lymphomas had a Y197 mutation." (PMID 36051079, 2022). "B-cell antigen receptor complex-associated protein CD79B, also known as B-cell-specific glycoprotein B29, Ig-beta and immunoglobulin-associated B29 protein, is a single-pass type I transmembrane protein receptor expressed in a number of lymphomas." (PMID 36498915, 2022). "There are typical recurrent mutations primarily affecting MYD88L265P and CD79B, placing PCNSL in alignment with the MCD (MYD88/CD79B-mutated) lymphoma molecular subtype of DLBCL which is also characterized by poor prognosis and extra-nodal involvement, especially in immune-privileged sites." (PMID 41226558, 2025). "The majority of CD79B-mutated lymphomas were localized in the testicles." (PMID 41295250, 2025). "In lymphomas, CD79B mutations also commonly co-occur with MYD88 mutations, especially MYD88L265P." (PMID 38203179, 2023). "Moreover, KLHL14 (Kelch-Like Family Member 14, a tumor-suppressing chaperone regulating protein folding, frequently mutated in lymphomas) promotes CD79a and CD79b ubiquitination and their consequent downregulation." (PMID 38203179, 2023). "Similarly, significantly reduced OS (p = 0.04) and PFS (p = 0.04) were observed for the CD79B mutated lymphomas in comparison with patients with CD79B WT." (PMID 36051079, 2022). "A high incidence of MYD88 and CD79B mutations was also detected in the ENT lymphomas in our cohort." (PMID 36051079, 2022). "Moreover, a recent study suggested that also synonymous variants may be involved in the pathogenesis of some diseases; therefore, one could speculate that this novel variant of CD79B gene could be involved in the pathogenesis of lymphomas." (PMID 23285191, 2012). "Our integrative NGS panel, covering the most recurrent lymphoma biomarkers, clearly demonstrated a higher ctDNA detection rate compared to relying solely on MYD88 and CD79B variants." (PMID 40346678, 2025).
lymphoma (continued). "CD79B mutations frequently co-occurred with MYD88 L265P, with 71% (n = 12) of CD79B-mutated lymphomas harboring a MYD88 mutation (p < 0.05)." (PMID 41295250, 2025). "Of note, several genes reflecting B cells (CD20/MS4A1, CD19, CD22, CD79B) were significantly highly expressed in HLA‐I+ compared to HLA‐I− lymphomas, suggesting that the prognostically favorable B‐cell‐rich TME is a feature of HLA‐I+ HL." (PMID 38836098, 2024). "Recently, PCNSL has been related to the so-called ‘MCD’ subgroup, which is a genetic subset of lymphomas with gain-of-function mutations in both MYD88 L265P and CD79B." (PMID 38730692, 2024). "We also observed significant variability in the surface expression of CD79b among lymphoma cases, with 18% showing predominantly intracellular positivity." (PMID 39682155, 2024). "Comparing CD79b expression between 16 BRH cases and 84 lymphoma cases, both analyzed with the DXFlex cytometer, we observed a CD79b strong expression (higher than 70%) in 97.5% of polyclonal B cells in BRH." (PMID 39682155, 2024). "In particular, it has been demonstrated that lymphoma levels of CD79b are strongly correlated with crosslinking BCR-induced signaling." (PMID 39682155, 2024). "CD79b (and CD79a) serves as critical signaling components of the B‐cell receptor that promotes lymphoma survival." (PMID 37206291, 2023). "The evaluation of the genes in association with BCR has revealed that targeting CD79A, CD79B, and LAMTOR4 as the shared genes can provide novel biomarkers for pSS progression into lymphoma." (PMID 37176092, 2023). "In mucosa-associated lymphoid (MALT) lymphoma, the chronic activation of the CD79B/BTK pathway enhances the proliferation of lymphoma cells." (PMID 37622116, 2023). "MYD88, CD79B, and/or BTK mutated lymphomas had a lower OS and PFS, which can mostly be attributed to the group of primary CNS lymphomas." (PMID 36051079, 2022). "We have demonstrated that an anti-CD79b/CD3 TDB is active against lymphoma cells, with a wide range of CD79b levels in vitro." (PMID 35631556, 2022). "Thirty‐four of 113 (30%) lymphomas harbored both MYD88 and CD79B mutations and were found in the breast (2/4; 50%), CNS (13/26; 50%), ENT (10/28; 36%), skin (5/16; 31%), testis (2/7; 28%), stomach (1/10; 10%), and PMBL (1/12; 8%)." (PMID 36051079, 2022). "Copanlisib, another PI3K inhibitor, is being used in combination with ibrutinib (NCT03581942) in order to address increased activation of the PI3K/AKT/mTOR pathway observed in CD79B mutant lymphomas." (PMID 34771535, 2021). "The CD79b mean fluorescence intensities (MFIs) of malignant lymphoma cells were similar to or higher than the MFI of normal B cells." (PMID 34256851, 2021). "It is also worth noting that while concurrent CD79B and MYD88 mutations appear to sensitize systemic lymphoma to ibrutinib, this same combination was associated with a poorer response in CNS disease, perhaps due to decreased dependence on the BCR pathway." (PMID 34771535, 2021). "Most cases have an ABC-like phenotype with upregulation of the NF-κΒ pathway, characteristically induced by EBV latent membrane protein-1 (LMP1), which explains the rarity of CD79B and MYD88 mutations in these lymphomas." (PMID 33178841, 2020). "In aggressive lymphomas, BTK inhibitors appear to be of particular benefit in lymphomas with activating mutations in MYD88 and CD79B." (PMID 33363034, 2020). "Since CD79b is highly prevalent in B cell leukemia and lymphomas, CD79b-targeted ADCs have been in active preclinical and clinical development." (PMID 30736842, 2019). "Studies in others extra-nodal lymphomas, such as central nervous system and testis lymphomas, also showed MYD88, CD79B and PIM1 as the most frequently mutated genes, and points out a common molecular profile for extra-nodal DLBCL." (PMID 29262531, 2017).
lymphoma (continued). "Of interest, the two SMZL cases with mutations of CD79B and MYD88, respectively, showed increased numbers of immunoblasts spread among the smaller and typical marginal zone lymphoma cells." (PMID 23378931, 2013). "These phenotypic characteristics have been shown to impact responses to small-molecular inhibitors and could render these lymphomas sensitive to the anti-CD79B antibody–drug conjugate polatuzumab vedotin with promising efficacy especially in the ABC DLBCLs." (PMID 38630892, 2024). "Notably, primary mediastinal B-cell lymphomas exhibited significantly lower surface CD79b expression compared to other lymphoma subtypes (median 0.8% IQR 0–48.5 vs. 80% IQR 24–97, p = 0.0005)." (PMID 39682155, 2024). "Mutations in CD79B reported to occur in 23% of IgM gammopathy–positive DLBCL, were found in 20% of lymphomas with IgM gammopathy and in 13% of lymphomas without IgM gammopathy, with 13% and 7% of the lymphomas harboring both a CD79B and a MYD88 mutation." (PMID 37566280, 2023). "However, more studies are necessary to elucidate the exact contribution of either CD79a or CD79b (and their mutations) to various types and states of BCR signaling in lymphoma." (PMID 38203179, 2023). "However, within the pathologically active BCR signaling in lymphoma, CD79A or CD79B mutations cannot be considered separately from other mutations." (PMID 38203179, 2023). "It is worth mentioning that enhancement of CD79b-mediated non-canonical NF-κB signaling has been associated with TRAF3 insufficiency in lymphoma." (PMID 38203179, 2023). "Polatuzumab, an antibody drug conjugates(ADC) antibody drug targeting CD79B, binds to the CD20 antigen, inhibiting B cell growth and proliferation in the CD79B region, and has been proven to have therapeutic effects in specific types of lymphomas, such as DLBCL and EMZL refractory or relapsed cases." (PMID 37622116, 2023). "Thirty‐four of 113 (30%) of the lymphomas harbored both MYD88 and CD79B mutations." (PMID 36051079, 2022). "Thirty percent of the lymphomas in our cohort harbored both MYD88 and CD79B mutations." (PMID 36051079, 2022). "Upon binding of the monoclonal antibody to CD79b, a signaling component of the B cell receptor, pola is internalized to the major histocompatibility complex class II positive compartment and the linker is cleaved by proteases for subsequent delivery of MMAE into the CD79b-positive lymphoma cells." (PMID 33258982, 2020). "CD79b is commonly used for the diagnosis of B cell leukemia and lymphomas." (PMID 30736842, 2019). "Indeed, gene markers known to be highly expressed by transitional and naïve B cells such as Membrane Spanning 4-Domains A1 (MS4A1), CD79B, and T-Cell Leukemia/Lymphoma 1A (TCL1A) were enriched in samples from ITx patients." (PMID 31134051, 2019). "Interestingly, the two cases with mutations of CD79B and MYD88 showed increased numbers of immunoblasts spread among the smaller and typical marginal zone lymphoma cells." (PMID 23378931, 2013). "In addition, CD79B transcripts are significantly more abundant than CD79A (fourfold increase) in some lymphoid cancer cell lines, suggesting that CD79B could act as a putative tumor promoter in leukemic B-cells." (PMID 40232347, 2025). "In conclusion, our observations regarding the heterogeneous surface expression of CD79b correlating with the intensity of the light chain expression in aggressive B-cell lymphomas align well with our existing comprehension of the role of the BCR complex in this particular subtype of lymphomas." (PMID 39682155, 2024). "Furthermore, lymphoma sequencing studies revealed that the network of concurrently mutated genes in MCD DLBCL cluster includes inactivating mutations of KLHL14, which promotes My-T-BCR-dependent NF-κB signaling via reduction of CD79a and CD79b ubiquitination." (PMID 38203179, 2023). "Therefore, CD79B may become a biomarker for lymphoma and provide valuable assistance for early prediction, diagnosis, and treatment of lymphoma." (PMID 37622116, 2023).
lymphoma (continued). "Thus, adding venetoclax to RCHOP-like regimens or to the MMAE-conjugated anti-CD79b antibody polatuzumab may be strategies to overcome the chemo-resistance associated in a subset of patients with BCL2+ high-grade lymphomas." (PMID 33670870, 2021). "We here describe the impact that MYD88 and CD79B activating mutations, two of the most frequent mutations in several DLBCL subtypes, may achieve in the next future in the diagnosis and therapeutics of such a relevant lymphoma subtype." (PMID 33050534, 2020). "These lymphomas arise from previously considered immune sanctuary sites and have inferior responses to treatment, are mostly of the non-GCB subtype of DLBCL, and have a high prevalence of combined MYD88/CD79B mutations in >70% of cases, resulting in constitutive NF-κΒ pathway activation." (PMID 33178841, 2020). "For lymphoma, molecules such as CD19, CD22, CD30, and CD79b are commonly targeted, highly expressed molecules." (PMID 40843358, 2025). "We recommend the routine assessment of CD79b expression in FO-LBCL cases and advocate for future clinical trials to evaluate the efficacy of polatuzumab vedotin in this and other rare lymphoma entities." (PMID 41383509, 2025). "Specifically, anti-CD79b monoclonal antibodies (mAbs), such as clone SN8, have demonstrated binding capabilities and efficient internalization into lymphoma cells, forming the rationale for developing ADCs as a treatment strategy for non-Hodgkin lymphomas." (PMID 39682155, 2024). "We confirmed that EBNA2 was a negative regulator of CD79A and CD79B in both LCL and lymphoma cell backgrounds and we also showed reduced CD79A and CD79B protein levels in response to EBNA2 activation in LCLs." (PMID 36383217, 2022). "We focused on highly expressed antigens found in primary leukemia and lymphomas, such as CD19, CD20, CD22, ROR-1, CD276, CD79B, and CD10." (PMID 36289682, 2022). "Anti-CD79b mAbs, specifically clone SN8, have been shown to bind and to be efficiently internalized into lymphoma cells for nearly three decades." (PMID 34358100, 2021). "It is noteworthy that the GB-749 glioblastoma hybrid tumor showed retention of glioma-related genes (PLAGL2, GFAP), whereas the lymphoma-derived hybrid tumor retained several B-cell antigen receptor (BCR)-related genes (CD19, CD20, CD71, CD79b)." (PMID 25259521, 2014). "Other genes, such as IKBKB, PTPRC, CASP8, or CD79B, with small p-values did not have a great magnitude of changes between the lymphoma subtypes." (PMID 41472741, 2025). "Most of the specimens with a CD79B mutation carried a concomitant MYD88 mutation and were classified as non-GCB lymphomas, which is in concordance to previous studies." (PMID 41295250, 2025). "Another study showed that TanCAR-T cells targeting CD79b/CD19 (but not targeting CD19/CD79b in the reverse order) successfully lysed CD19- lymphoma within a heterogeneous tumor." (PMID 40092990, 2025). "Pathogenic variants were obvious in some of the most commonly affected genes in lymphomas, such as BCL2, MYD88, NOTCH2, EZH2, and CD79B, and most of them could be identified in matched LB-originated cfRNA." (PMID 34204385, 2021). "The most frequently mutated genes (PIM1, MYD88, CD79B, and CARD11) are more prevalent in non-GCB DLBCL as has been addressed in previous publications in both extra-nodal and nodal lymphomas." (PMID 29262531, 2017). "In addition, anti-CD79b/CD3 TDB administration inhibited tumor growth in B cell lymphoma xenograft models and resulted in potent B cell depletion in the blood and spleens in a humanized murine model of lymphoma." (PMID 35631556, 2022). "Given that CD79b plays a crucial role in mediating signaling through the BCR upon antigen binding, we can only speculate on the functional consequences of the low or absent expression of CD79b and its potential impact on the alteration of the signaling pathway in lymphoma cells." (PMID 39682155, 2024).
lymphoma (continued). "Thus, we suggest that the overactivation of BCR-related genes such as CD79A, CD79B, and LAMTOR4 as the shared overexpressed genes among DLBCL, pSS peripheral, and SGs could be involved in pSS progression into lymphoma and probably be responsible for the failure of Rituximab therapy." (PMID 37176092, 2023). "For CD79B, irrespective of MYD88 mutational status, mutations were found in 4/28 (14%) of ENT lymphomas, 2/26 (8%) of CNS lymphomas, 2/7 (28%) of lymphoma of the testis, 1/8 (12%) of bone lymphomas, 1/2 (50%) of lymphomas located in the spleen, and 1/16 (6%) of skin lymphomas." (PMID 36051079, 2022). "In general, CD19CAR T cells become non-functional in CD19 negative lymphoma subsets; however, AdCAR T cells can be redirected to alternative target antigens beyond CD19, such as CD20, CD22, CD79B, and ROR-1." (PMID 36289682, 2022). "While for the other 4 cases whose BM involvement was diagnosed by flow cytometry, their lymphoma cells were positive for CD20, CD22, CD79b, and the surface light chain, while negative for CD138." (PMID 34503477, 2021).